EGFR (epidermal growth factor receptor)
Diseases named in the same sentence as EGFR in open-access papers (continued):
Sharing a sentence is not in itself a finding about the gene and the disease.
cancer (continued). "Therefore, c-Met is considered as an attractive target biomarker for cancer therapy, particularly for EGFR-TKI resistant cancer." (PMID 31060329, 2019). "Additionally, EGFR was found to inhibit RHOB promoter activity in cancer cells derived from pancreatic (Panc-1) tumors, cervical (C33A) tumors, and lung (A549) tumors." (PMID 31200451, 2019). "Alternatively, TKIs may be sequestered in lysosomes, protonated, and subsequently removed from cancer cells by exocytosis or via the efflux transporters, thereby precluding the interaction of TKIs with EGFR." (PMID 31266248, 2019). "Thus, we believe that the SPT-based EGFR dynamics can serve as a new biophysical assay to probe the metastatic potential of cancer cells and to monitor their response to anti-cancer drug treatments." (PMID 31805710, 2019). "Since EGFR is a driver of tumorigenesis, hyperactivation of EGFR signaling pathways caused by CGRRF1 promoter hypermethylation and downregulation seen in many types of cancer may contribute to cancer progression." (PMID 31801577, 2019). "This highlights the feasibility of blood-based EGFR testing in diagnosis and monitoring of cancer." (PMID 31582907, 2019). "A plethora of literature points to the association between these mutations and resistance to common therapies especially anti-EGFR treatment as well as cancer progression, highlighting the need to detect PIK3CA p110α mutation as a strong predictive and prognostic biomarker." (PMID 32099598, 2019). "However, despite the overexpression of EGFR in these cancers, the initial response rates to cetuximab monotherapy are far from encouraging, and furthermore, treatment responses rapidly decline after a short period of effect." (PMID 30700700, 2019). "Similarly, EGFR is a relevant biomarker of aggressiveness and resistance to therapy, highly expressed in many types of cancer, and therefore, it appears as a promising target for in vivo imaging." (PMID 31182936, 2019). "Finally, we show that these photoactive antibodies mediate light‐dependent delivery of small molecule fluorophores to the surface of EGFR‐positive live cancer cells." (PMID 31609054, 2019). "Unexpectedly, we identified BCAP31 as an important mediator of ligand-independent EGFR signalling to promote cancer development in TNBCs, and our study more broadly reveals that the collaboration between BCAP31 and EGFR can be exploited for therapeutic interventions." (PMID 31588230, 2019). "This study suggests that kinase-inactivated EGFR remains to be a viable therapeutic target for wt-EGFR cancers and that inhibiting palmitoylation or downregulating EGFR may overcome TKI resistance." (PMID 31121829, 2019). "As current EGFR inhibitors are associated with different drug resistance mechanisms, EGFR aptamer may prove useful in the treatment of cancers that are resistant to current EGFR inhibitors." (PMID 31546749, 2019). "Moreover, miRNA-mediated inhibition of EGFR triggered remarkable spontaneous apoptosis and increased sensitivity of the cancer cells to erlotinib-mediated apoptosis." (PMID 31554377, 2019). "However, many oncogenes and oncogenic pathways (e.g., c-Myc, EGFR, Akt, mTORC1, Ras/Raf, and others), which regulate normal growth, are valid targets for cancer therapy." (PMID 30962446, 2019). "Activation of the EGFR signaling pathway plays a crucial role in many aspects of cancer biology." (PMID 30532069, 2019). "The promotion of cancer cell proliferation may be due to activating the mitogenic signalling by modulating epidermal growth factor receptor (EGFR) activation through Cbl and GTPases Cdc42." (PMID 30621321, 2019). "Interestingly, transmembrane proteins and proteins coupled to receptor activity, such as the cancer-related EGFR and TGFBR3, were also tightly regulated." (PMID 30958262, 2019). "In this regard, we speculate that kinase-inactivated EGFR in TKI-treated cancer cells may be required for cell survival and facilitate resistance." (PMID 31121829, 2019).
cancer (continued). "EGFR is the most commonly expressed/overexpressed membranous oncogenic protein in cancer." (PMID 31508364, 2019). "Additionally, cancer cell migration connected with epithelial-mesenchymal transition is enhanced by activation of EGFR." (PMID 31649529, 2019). "Understanding how cancer cells respond to EGFR inhibitor treatment could help determine how likely a patient is to develop resistance to these drugs." (PMID 31741433, 2019). "EGFR amplification was detected in cfDNA among 8.5% of 28,584 diverse cancers." (PMID 31058253, 2019). "As one of the most investigated tyrosine kinases, EGFR over-expression has long been associated with the development of a number of cancers and believed to be a negative cancer prognostic factor." (PMID 31546749, 2019). "Cancer cells can even transfer activated EGFR to macrophages and thereby suppress innate immunity." (PMID 30910997, 2019). "Interestingly, the signaling pathway enrichment analysis indicated that epidermal growth factor receptor and protein kinase B, which is closely related to cell growth, proliferation, and apoptosis, play a critical role in cancer." (PMID 31171715, 2019). "Collectively, our study demonstrated that DYRK1A could positively regulate the STAT3/EGFR/Met axis and DYRK1A suppression could enhance the anti‐cancer activity of AZD9291 via STAT3 pathway in EGFR wild‐type NSCLC cells." (PMID 31454149, 2019). "Furthermore, this study found that the sodium/glucose co-transporter 1 (SGLT1) played a critical role in mediating the KID pro-survival function of EGFR by maintaining active glucose uptake of cancer cells." (PMID 31508364, 2019). "Despite the well-explored but rarely occurred genetic alterations like mutations can led to the dysregulation of EGFR, the aberrant expression of EGFR in various types of cancers suggests the existence of one or several more general pathophysiological mechanisms for regulating EGFR expression." (PMID 30683916, 2019). "Furthermore, Rab1A was associated with S6K levels in 7 cancers, with Gli1 in 2 cancers, AKT in 7 cancers, HER2 in 2 cancers, and with EGFR in 6 cancers." (PMID 31527621, 2019). "After comparing the drug response of single-cell and cancer spheroid models, it was shown that the spheroid model could narrow down the list of drug candidates by identifying high-efficacy p-EGFR-targeting drugs." (PMID 31614722, 2019). "Constitutively active MAPK signaling in KRAS-mutated CRC promotes epithelial–mesenchymal transition and cancer stemness, independent of external EGFR stimulation." (PMID 31771279, 2019). "In a cancer cell line, the increased sensitivity to antagonists of an oncogenic epidermal growth factor receptor was revealed upon siRNA-based inactivation of SC4MOL and NSDHL leading to 4,4-dimethylzymosterol, 4-methylzymosterol, or 4-carboxysterol accumulation." (PMID 30691248, 2019). "Therefore, targeting the kinase-inactivated EGFR in TKI-treated/resistant cancer cells holds therapeutic value." (PMID 31121829, 2019). "Taken together, these results showed that endocytic degradation of EGFR leads to depletion of the receptor, which drastically destabilizes the cytoskeleton, leading to the detachment of cancer cells from the ECM and, ultimately, to death, resembling apoptotic anoikis." (PMID 31374910, 2019). "Indeed, Rituximab, an anti-CD20 antibody, was the first monoclonal antibody approved for cancer therapy in 1997, being followed by several others, including Cetuximab (anti-EGFR) and Trastuzumab (anti-HER2), all of the IgG isotype." (PMID 31817406, 2019). "As the EGFR diffusivities are clearly (negatively) correlated with the LD scores, we can potentially use TReD to replace LD scores in quantifying the differentiation potency of cancer cells." (PMID 30833579, 2019).
cancer (continued). "Downregulation of EGFR or inhibition of EGFR kinase may halt the proliferation of cancer cells; thus, many tyrosine kinase inhibitors such as gefitinib, lapatinib, and erlotinib have been developed; however, only limited effectiveness were achieved." (PMID 31354907, 2019). "In addition, we discuss new developments concerning anti-autophagy therapeutics for overcoming resistance to anti-EGFR treatments in various cancers." (PMID 31527477, 2019). "Although activation of FGFR signaling may also contribute to acquired EGFR-TKI resistance in EGFR-mutant cancer." (PMID 31791326, 2019). "However, acquired and innate resistances have precluded current anti-EGFR agents from offering sustainable benefits to initially responsive cancers and benefits to EGFR-positive cancers that are innately resistant." (PMID 31508364, 2019). "Thus, the EGFR pathway is the major mechanism of the reversal effect of IVM on the resistant cancer cells." (PMID 31215501, 2019). "One of these could be the TF NF-κB, which is activated in response to EGFR-TKIs, drives survival of EGFR-dependent cancer cells, and whose genetic or pharmacologic inhibition can potentiate erlotinib-induced apoptosis in NSCLC models." (PMID 31266248, 2019). "The EGFR expression has been reported to increase in many cancers." (PMID 31554377, 2019). "However, the success of EGFR-based therapy was compromised by therapeutic resistance following initial treatment response in most cancer patients." (PMID 31816897, 2019). "Furthermore, EGFR has been demonstrated to modulate glucose level in cancer cells by regulating sodium/glucose cotransporter 1 (SGLT1) independent of receptor tyrosine kinase activities." (PMID 30791926, 2019). "However, it is unclear how other proteins in cancer cells affect the response to these EGFR inhibiting drugs." (PMID 31741433, 2019). "Moreover, the C‐dots disrupt DNA repair through BER pathway and inhibits cancer cell proliferation likely through mTOR, Pim‐1, EGFR, and DNA damage pathways." (PMID 31692950, 2019). "However, when it comes to the utilization of these well-established theories to target EGFR for cancer therapy, the reality has raised some questions challenging the comprehensiveness of our knowledge on EGFR in cancer." (PMID 31508364, 2019). "In contrast, in cancer cells that lack DUOX1, abnormal dynamics of EGFR cysteine oxidation are associated with aberrant EGFR trafficking and nuclear localization, although the precise molecular mechanism(s) by which this occurs remain unclear." (PMID 30890751, 2019). "Interestingly, it has been reported that overexpression of EGFR in cancer cells plays a role in accelerated proteolysis of p27 protein and allow the cancer cells to undergo rapid division and uncontrolled proliferation." (PMID 31139331, 2019). "Collectively, our results suggested that harmine might sensitize the anti‐cancer activity of AZD9291 via the STAT3/Met pathway in EGFR wild‐type NSCLC cells." (PMID 31454149, 2019). "We also assess whether autophagy inhibition, along with anti-EGFR treatments, might represent a promising approach to overcome resistance to anti-EGFR treatments in various cancers." (PMID 31527477, 2019). "Finally, we demonstrate the application of photoactive antibodies in delivering fluorophores to EGFR‐positive live cancer cells in a light‐dependent manner." (PMID 31609054, 2019). "However, little is known about the molecules that control protein quality in the ER and their oncogenic roles in cancer development together with EGFR signalling." (PMID 31588230, 2019). "In turn, NRP1 can complex with EGFR, which is overexpressed and active in many cancer cells." (PMID 30717262, 2019). "EGFR is known to play a key role in the progression of various cancers, including renal cancer." (PMID 30770799, 2019). "In addition, Rab1a was correlated to S6K in 7 cancers, Gli1 in 2 cancers, AKT in 7 cancers, HER2 in 2 cancers, and EGFR in 6 cancers." (PMID 31527621, 2019).
cancer (continued). "Two major unmet challenges have stymied the efficacy of EGFR targeted cancer therapies." (PMID 31508364, 2019). "We hypothesized that EGFR downstream of STAT3 participates in HER3 expression because STAT3 contributes to cancer stemness and survival of EGFR-TKI resistant cancers." (PMID 31619200, 2019). "In this review, we summarized the downstream targets of Pyk2 in cancers, focused on the connection between Pyk2 and EGFR signaling pathway in different cancer types, and provided a new overview of the roles of Pyk2 in EGFR signaling pathway and cancer development." (PMID 31368612, 2019). "Thus this provided conclusive evidence that anti-EGFR-antibody-GNRs injected intratumorally became endocytosed within cancer cells, where they were optimally poised for subsequent PTT." (PMID 30899637, 2019). "Studies of the resistance mechanisms to EGFR-targeted drugs suggested that concomitant activation of other signaling systems in the cancer cells may be one of the reasons." (PMID 31515263, 2019). "As most adjuvant cancer treatments are combinations of chemotherapeutic agents and/or radiotherapy, we are convinced that new EGFR-targeted agents, such as afatinib, will achieve their greatest efficacy in combination with traditional cytotoxic agents and/or radiotherapy." (PMID 30650638, 2019). "Thus, it is valuable to predict therapeutic response by detecting the sequence of miR-21 in biopsies from cancer patients before they receive treatments such as EGFR tyrosine kinase inhibitors." (PMID 31816897, 2019). "Indeed, activation of the EGFR autocrine growth pathway is a common mechanism for cancer cell proliferation, adhesion, migration and invasion in different types of epithelial cancers including CRC." (PMID 31557914, 2019). "However, there were still many cancer promoting factors being increased, such as EGFR, G-CSF, CXCL6, etc.." (PMID 30805774, 2019). "Additionally, PKM2 also acts as a protein kinase in the nucleus upon EGFR activation, hypoxia or glucose depletion, where it can enhance the proliferation and survival of certain types of cancer cells in response to mitogen activation or hypoxic stress." (PMID 31120964, 2019). "Besides EGFR’s kinase function, which is prominently implicated in cellular growth and proliferation, emerging evidence shows that EGFR possess kinase-independent function that is critical for survival of cancer cells." (PMID 31121829, 2019). "We determined that the coexistence of genetic alterations in cancer genes may explain primary resistance to EGFR-TKIs." (PMID 30823937, 2019). "As dysregulation of EGFR is intimately associated with the oncogenesis and metastasis of different cancers 25, we hypothesized that BCAP31 promotes cancer development through regulation of the EGFR signalling pathway." (PMID 31588230, 2019). "Pyk2 and EGFR signaling pathway are both proved to decide the fate of cancer." (PMID 31368612, 2019). "EGFR, a cell surface receptor having a TK domain, has been focused as a molecular target of cancer treatment, because its abnormal activation and overexpression have been observed in several malignant tumors." (PMID 31100782, 2019). "Our data suggest that the EGFR/Eps8 complex offers a novel cancer drug target." (PMID 31118055, 2019). "To further validate the pathological implications of HSP70 phosphorylation in cancer cells, we analyzed the basic phosphorylation of HSP70 in the absence of EGF signaling in normal and cancerous lung cells harboring mutations in EGFR or K-Ras, which is a well-studied activator of ERK28." (PMID 31558706, 2019).
cancer (continued). "Since cancer cells of epithelial origin can express IL-1R2, it is possible that in our case cetuximab/EGFR inhibition may be inducing the release of IL-1β as well as IL-1α but we are unable to detect IL-1β due to rapid binding by sIL-1R2." (PMID 30890189, 2019). "Since both EGFR-TKIs and curcumin induce autophagy in cancer cells, we infer that curcumin can enhance inhibitory effect of gefitinib on primary EGFR-TKI resistant NSCLC cells through augmenting gefitinib-induced autophagy and inducing autophagy-related cell death." (PMID 31196210, 2019). "The EGFR/Eps8 complex is involved in regulating cancer progression and might be an ideal target for antitumor therapy." (PMID 31118055, 2019). "Transwell, western blot, and tube formation results proved that L14e could inhibit the activation of the EGFR signaling pathway, then ultimately achieve the purpose of inhibiting cancer cell migration and angiogenesis in cancer tissues." (PMID 31296849, 2019). "Recent studies suggest that a substantial portion of the effects attributed to EGFR antagonist treatment may be based on indirect effects beyond cancer cells." (PMID 31370270, 2019). "Using an on‐cell assay, we show that the presence of a photocaging group at specific tyrosine residues in the antigen binding region of 7D12 inhibits its binding to EGFR on the surface of cancer cells and the binding is restored upon irradiation with 365 nm light." (PMID 31609054, 2019). "The number of EGFR-positive exosomes seemed to be well correlated with patient cancer stages." (PMID 31792209, 2019). "The ability of the active compounds VM25 and VM26 to simultaneously suppress tyrosine phosphorylation and to reduce EGFR levels and other functionally unrelated proteins suggested that the small molecules induce protein degradation by first targeting EGFR in cancer cells." (PMID 31374910, 2019). "EGFR is regarded as an early marker for the early detection of cancer in oral dysplasia." (PMID 31540512, 2019). "Furthermore, the conjugation of the anti-EGFR aptamer with the immunomodulatory antibody allowed for the efficient redirection and activation of T cells against cancer cells, thus dramatically enhancing the cytotoxicity of the two conjugated partners." (PMID 31470510, 2019). "Summarize the results of inhibition of transwell and tube formation, proved that L14e could inhibit the activation of the EGFR signaling pathway and ultimately achieve the purpose of inhibiting cancer cell migration and angiogenesis in cancer tissues." (PMID 31296849, 2019). "Together with our findings, LAPTM4B may interact with EGFR and play an important role in the pro-survival functions of EGFR in cancer cells." (PMID 30940109, 2019). "The combination treatments of Pyk2 inhibitors with molecules that target carcinogenic EGFR signaling pathway may help acquiring better clinical outcomes of anti‐cancer treatment." (PMID 31368612, 2019). "Together, these data highlighted the SSP as a metabolic vulnerability in EGFR-mutant cancer." (PMID 31221965, 2019). "Together, drug combination perturbs survival pathways in cancer cells, such as EGFR and β-catenin." (PMID 31514441, 2019). "That EGFR activation contributes to cancer is implicit from decades of research." (PMID 31857847, 2019). "Frequencies of EGFR amplification differed between cancer types." (PMID 31058253, 2019). "Cancers may acquire activating mutations in exon 2 of KRAS, thus isolating the signaling pathway from the effect of upstream EGFR2, rendering the EGFR inhibitors ineffective." (PMID 30975211, 2019). "However, the rate of EGFR mutations in OSCC, which ranges from 2.7% to 8%, is lower than that in other cancers 39–41." (PMID 30914776, 2019). "However, it seems that these compounds presented higher inhibitory activity against the wild type EGFR (A431) than the two mutant EGFR cancer cell lines." (PMID 30897725, 2019).